LAG3 (lymphocyte activating 3)
Diseases named in the same sentence as LAG3 in open-access papers (continued):
Sharing a sentence is not in itself a finding about the gene and the disease.
cancer (continued). "We found CD47 had strong correlation with CD274, LAG3, IDO1 and TNF receptor superfamily in pan-cancer(r > 0.2, p < 0.05)." (PMID 38720108, 2024). "Then, immune checkpoints analysis shown that UBE2C had a negative correlation with immune checkpoints, such as CD274(PD-1), PDCD1(PD-L1), CTLA4, TIGIT, LAG3, HAVCR2, and PDCD1LG2 in a great many cancers." (PMID 38370368, 2024). "Drugs directed against TIGIT, ILT4, LAG-3, TIM-3 or therapeutic cancer vaccines are currently being studied in early-phase clinical trials, showing promising results." (PMID 39407796, 2024). "The present study indicated ADAM10 expression regulation by AD, CD and m62A, and in AD/ADAM10/LAG3 or CD/ADAM10/LAG3 signaling in cancers, suggesting a potential method for immunotherapy of cancers by targeting ADAM10 using the small molecules AD, CD and m62A." (PMID 39211038, 2024). "Our study thus reveals a role of TSs in regulating metastasis via non-cell-autonomous modulation of the immune compartment and provides proof-of-principle for ICB targeting LAG3 for patients with NF1-, TSC1- or TGF-β RII-inactivated cancers." (PMID 38997291, 2024). "The interaction of LAG-3 with its ligands, such as MHC-II, Galectin-3, LSECtin, and FGL-1, highlights its potential as a therapeutic target and prognostic biomarker for cancer." (PMID 39660130, 2024). "The exhaustion of CD8 + T and NK cells, along with the overexpression of molecular markers such as LAG3, CTLA4, CD274, PD-L1, and HAVCR2, have been identified as key mechanisms by which cancer cells can escape host immunity." (PMID 38956740, 2024). "Downregulation of FOXP3 in cancer Tregs was accompanied by significantly decreased mRNA expression of five out of nine tested exhaustion markers: CTLA-4, Tim-3, PD-1, LAG-3 and TIGIT in the endogenous T cells." (PMID 39234236, 2024). "A group of ICPs, including but not limited to PD-1/PD-L1, CTLA-4, lymphocyte activation 3 (LAG-3), TIM-3, VISTA, and indoleamine 2,3-dioxygenase 1 (IDO1), are shown to be dysregulated in cancer and infectious diseases." (PMID 38638433, 2024). "We initially explored the expression of the Tex signature genes (LAG3, TIGIT, LAYN, PDCD1, HAVCR2, and CXCL13) in pan-cancer." (PMID 39064019, 2024). "For example, TOP2A, LAG3, SLAMF7, and PTGS2 are established or promising key targets for cancer treatments and immunotherapy." (PMID 38746418, 2024). "Subsequently, we also explored the correlation between the expression levels of LRP6 and the expression levels of common immune checkpoints in 33 cancers, such as SIGLEC15, IDO1, CD274, HAVCR2, PDCD1, CTLA4, LAG3 and PDCD1LG2." (PMID 38226972, 2024). "Immune checkpoint blockade (ICB) has undoubtedly changed the landscape of cancer therapies, with PD-1, CTLA-4, and PD-1/LAG-3 therapies becoming FDA-approved for use in multiple malignancies, leading to improved survival for many patients." (PMID 39199630, 2024). "Due to the blocking mechanisms of anti-LAG-3 and anti-TIGIT, it is assumed that simultaneous blockade of LAG-3 and TIGIT would be a novel strategy for cancer immunotherapy." (PMID 38724599, 2024). "Inhibitory receptors have been identified in cancers, including but not limited to PD-1, CTLA-4, LAG3, and TIM3, etc.." (PMID 38627727, 2024). "The emergence of ICIs, mainly including PD-1/PD-L1, LAG-3, and CTLA-4 monoclonal antibodies (mAbs), has shaped the therapeutic landscape of some types of cancers." (PMID 39687617, 2024). "LAG-3, TIM-3 and TIGIT biology and its role for treatment of cancers has been reviewed in detail elsewhere." (PMID 38322418, 2024). "Both AD and CD inhibited LAG3 expression in vitro, indicating the possible pathways of AD/ADAM10/LAG3 or CD/ADAM10/LAG3 in anti-cancers, or suggesting a potential method for immunotherapy of cancers." (PMID 39211038, 2024). "Lastly, we conducted a pan-cancer analysis, revealing significant correlations between ALPK1 and various immune checkpoints, including PD-L1, CTLA-4, LAG-3, and PDCD1." (PMID 39845963, 2024).
cancer (continued). "At least one of the ICs—TIM3, IDO, B7H4, LAG3, VISTA or PD-L1—was present in cancers cells in 66.2% (n = 45) of resected tumors." (PMID 36768480, 2023). "In our survey of LAG-3 expression across cancer types, DLBCL showed frequent and high levels of LAG-3 expression." (PMID 37857711, 2023). "Our result showed that several immune escape related signals on the cancer cell surface are significantly up‐regulated, including PD‐L1, LMTK3 and LAG3." (PMID 36058633, 2023). "Persistent exposure to cancer antigens induces CD4 T cell exhaustion by upregulating the expression of several co-inhibitory markers, including PD-1, CTLA-4, TIM-3, and Lag-3, and downregulating the production of cytokines such as IFN-γ18." (PMID 37147330, 2023). "mAbs targeting CTLA4, PDCD1, CD274, and LAG3 have been approved by the FDA for second- and first-line treatment against cancer, whereas mAbs targeting ICOS and CD40 are under investigation." (PMID 37215135, 2023). "We analyzed the expression profile of COMMD2 gene and ICGs (CD274, CTLA4, HAVCR2, LAG3, PDCD1, PDCD1LG2, SIGLEC15, and TIGIT) at a pan‐cancer level." (PMID 36205192, 2023). "The adenosine A2A and A2B receptors, CD47-SIRPα, TIM-3, LAG-3, TIGIT, and VISTA are targets that also contribute to cancer immunoresistance and have been considered for clinical trials." (PMID 36829496, 2023). "In specific, TIS is referred to as an 18‐gene signature (CCL5, GZMK, CD3D, CD3E, CD2, HLA‐DRA, IL2RG, NKG7, CIITA, CXCR6, LAG3, TAGAP, HLA‐E, CXCL13, IDO1, CXCL10, STAT1, and GZMB), which was related to the response to ICIs in various cancers." (PMID 37434432, 2023). "We found that PTPN6 expression was positively correlated with PDCD1, CD274, CTLA4, LAG3, HAVCR2, and CD244 in most cancer types in TCGA, including LGG and GBM." (PMID 37737713, 2023). "Other immune checkpoints, including LAG‐3, TIM‐3 (also known as HAVCR2), TIGIT, and VISTA, have emerged as promising targets in cancer immunotherapy." (PMID 37904707, 2023). "LAG-3 expression significantly increased in patients with advanced stages, FIGO stages III and IV (P = 0.036), and in cases of cancer recurrence (P = 0.012)." (PMID 37179337, 2023). "Here, we discuss which types of cancer TIM-3 can serve as a prognostic factor and the influence of coexpressed immune checkpoint inhibitors, such as LAG-3, PD-1, and CTLA-4 on patients' outcomes." (PMID 37567938, 2023). "Among these cancers, TGCT, OV and UCS displayed the highest frequency of LAG3 amplification, while UCEC and SKCM had the highest frequency mutation." (PMID 38115039, 2023). "Through our pan-cancer analysis, we found that CEP55 was significantly correlated with MDSCs and Th1 cells in most cancers and positively correlated with the expression of checkpoints, such as PD1, CTLA4, LAG3, and TIGIT in certain cancer types." (PMID 37484531, 2023). "However, a previously published meta-analysis showed that the overexpression of LAG3 was correlated with a more favorable OS in several types of cancer, which could be attributed to the limited number of included studies and the enrollment of a large number of patients with early-stage cancer." (PMID 38041068, 2023). "Interactions of the immune checkpoint molecules LAG3‐LGALS3 and TIGIT‐NECTIN2 between CD8+ T cells and cancer/immune/stromal cells are found to play dominant roles in the immune escape." (PMID 36529697, 2023). "A number of inhibitory immunoreceptors have been identified and studied in cancer in past decades, including but not limited to PD-1, PD-L1, CTLA-4, LAG3, HAVCR2, TIGIT, CD69 and CD40." (PMID 37989761, 2023). "Checkpoint molecules such as PD-1, LAG-3, and TIM-3 are currently under extensive investigation for their roles in the attenuation of the immune response in cancer." (PMID 37895833, 2023). "PD-1, CTLA4, LAG3, and HAVCR2 are T cell depletion markers, and the T cell depletion is a major factor contributing to immune dysfunction in cancer patients." (PMID 36785788, 2023).
cancer (continued). "Cancer cells can evade the immune system by upregulating inhibitory receptors and ligands on their cell surface, such as CTLA-4, PD-1, PD-L1/2, Lag-3, and Tim-3." (PMID 38136253, 2023). "T cell exhaustion is a state of T cell dysfunction that occurs during many chronic infections and cancers; during this process CD8 T cell-TNF (effector CD8 T cells) gradually transform into CD8 T cell-LAG3 (exhausted CD8 T cell) from HBV cirrhosis to HBV HCC." (PMID 38116005, 2023). "In all cancer types, AFAP1L2 was present in clusters of PD-1+ CD8+ T cells that express exhaustion markers such as LAG3, TIM-3, and CD39." (PMID 37388918, 2023). "It is conceivable that the fusion WT NVs platform can be extended to concurrently targeting to other checkpoints for synergetic cancer immunotherapy except PD‐1/PD‐L1 and SIRPα/CD47, such as CTLA‐4, LAG‐3, TIGIT and so on." (PMID 37974395, 2023). "Exhausted T cells in cancer express high levels of inhibitory receptors, including PD-1, CTLA-4, TIM-3, LAG3, BTLA, and TIGIT, most of which are also known as Treg markers." (PMID 36901957, 2023). "Other immune checkpoint pathways, such as LAG-3 and TIGIT, are also being investigated as potential targets for cancer therapy." (PMID 37031434, 2023). "In another attempt, using the cancer genome atlas (TCGA) and METABRIC data, a ‘high’ LAG-3 expression pattern was more common in HR-negative and HER2-negative groups, as well as TNBC, and tumors with higher stages and grades." (PMID 37264298, 2023). "In this review, the role of five ICs, viz., VISTA, TIGIT, LAG-3, TIM-3, and PD-1, will be examined in cancer progression, metastasis, and clinically refractory cases." (PMID 37345111, 2023). "Several inhibitory immunoreceptors have been discovered and studied in cancers, and apart from PD-1 also include CTLA-4, LAG3, TIM3, TIGIT, BTLA, etc." (PMID 38067344, 2023). "Another clinical study using the bispecific PD-1 and LAG-3 protein includes unrespectable or metastatic neoplasms tumors, including HER2+ advanced cancer and TNBC (NCT03219268)." (PMID 37174080, 2023). "Here we report that treatment of human lymphocytes with cfChPs isolated from sera of cancer patients led to marked activation of the immune checkpoints PD-1, CTLA-4, LAG-3, NKG2A, and TIM-3." (PMID 38274821, 2023). "The LAG3–MHC II interaction can reduce T-cell proliferation and protect cancer cells from drug-induced apoptosis." (PMID 37895833, 2023). "Other antibodies targeting stimulatory or inhibitory coreceptors, including OX40, LAG-3, CD70, and GITR, are being tested in cancer studies as Afuc forms to enhance antibody immunomodulatory functions in vivo." (PMID 35775486, 2022). "Therefore, combined PD-1 and LAG-3 inhibition may be a promising immunotherapy program for cancers." (PMID 35494015, 2022). "The upregulation and sustained expression of co-inhibitory receptors such as LAG-3, TIM-3 and programmed cell death protein-1 (PD1) is an indication of T cell exhaustion and it is usually found in chronic infections and cancer." (PMID 35065613, 2022). "Immune checkpoints that play roles in immune tolerance of various cancers include T cell immunoglobulin-3 (TIM-3), V-domain Ig-containing suppressor of T cell activation (VISTA), and lymphocyte-activation gene 3 (LAG-3)." (PMID 36429020, 2022). "Afterward, we evaluated the link between DTYMK expression and key immune checkpoints (CD274, CTLA-4, HAVCR2, LAG3, PDCD1, PDCD1LG2, SIGLEC15, and TIGIT) expression levels in pan-cancer." (PMID 36094557, 2022). "We examined the correlation between the transcriptomic expression of SPINK1 and a number of critical ICPs—PD-1, LAG-3, TIM-3, TIGIT, and CTLA-4—which are the likely signatures for the response to ICB in cancer immunotherapy." (PMID 35924241, 2022). "The emergence of immunotherapy has shed light on cancer therapy; TMB and immune checkpoints, such as PD-L1, CTLA-4, LAG3, TIM3, and TIGIT, act as gatekeepers or biomarkers of immune responses." (PMID 35493104, 2022).
cancer (continued). "The key immune checkpoints (CD274, CTLA-4, HAVCR2, LAG3, PDCD1, PDCD1LG2, SIGLEC15, and TIGIT) also had a significant relationship with DTYMK expression in approximately 20 kinds of cancers, except in MESO, PCPG, and UCS." (PMID 36094557, 2022). "We found that PTBP expression showed a strong correlation with PD-1, CTLA4, LAG3, or TIM-3 in pan-cancer." (PMID 36203873, 2022). "Preclinical studies have shown that blockade of the PD-1 pathway upregulates LAG-3 and combinatorial inhibition of LAG-3 and PD-1-PDL-1 axis in cancer exhibit durable antitumor response." (PMID 36135216, 2022). "LAG-3 on CD4+ cells likely interacts with MHC class II on antigen-presenting cells, while LAG-3 on CD8+ T cells and NK cells likely interacts with L-SECtin on cancer cells." (PMID 35205776, 2022). "The expression of additional immune checkpoints in various cancer types has also been described, such as T-cell immunoglobulin and mucin-domain-containing-3 (TIM-3), lymphocyte activation gene-3 (LAG-3), and T-cell immunoglobulin and ITIM domain (TIGIT)." (PMID 35207374, 2022). "Among exhaustion markers, TIM3, LAG3, and PD1 are highly expressed on T cells in several cancer types and their triple knockdown can enhance CAR T cell antitumor functions." (PMID 36591284, 2022). "Lymphocyte activation gene-3 (LAG3; CD223) is a promising target for cancer immunotherapy because it negatively regulates T-cells and binds to PD1 to mediate exhausted state." (PMID 36226174, 2022). "LAG3Ab blocks the binding between LAG3 expressed on DNT cells and its ligands, such as MHC‐II, expressed on cancer cells to enhance the cytotoxicity of DNT cells." (PMID 35894707, 2022). "For example, immunosuppressive checkpoint proteins such as PD-1, CTLA-4, LAG-3, TIM-3, and NKG2A/B and are often upregulated in cancer." (PMID 35205776, 2022). "TME substances can induce angiogenesis and the development of cancer and metastasis, whereas the immune cells found in TME, namely, CTLA-4, PD1, PD-L1, LAG3, and VISTA participate in the antitumor immune response." (PMID 35744019, 2022). "In this study, we found that patients in the low-risk subgroup had higher expression of common immune checkpoint molecules such as PD-1, PD-L1, LAG3, CTLA-4, PD-L2, and CD74, which are commonly expressed in human cancer." (PMID 35996170, 2022). "AP3S1 expression was positively correlated with most immunosuppressive genes in pan-cancer, such as the common CD274 (PD-L1), PDCD1 (PD-1), CTLA4, LAG3, and TIGIT." (PMID 35874816, 2022). "BAP1-mutant UMs display a suppressive TIME enriched for M2 polarized macrophages and T cells expressing checkpoint or “exhaustion” markers such as LAG3, TIM3, and TIGIT, similar to findings in other cancer types." (PMID 35954340, 2022). "RALA was significantly correlated with the infiltration of B cells and macrophages, as well as the expression of immune checkpoint molecules such as CD274, CTLA4, HAVCR2 and LAG3, suggesting that RALA can be used as a kind of new pan-cancer immune marker." (PMID 36466919, 2022). "Other potential immune checkpoints, such as LAG3, CD96, PDCD1, BTLA, IDO1, and TIGIT, were also enriched in PTPRD/PTPRT mutant cancers." (PMID 36248841, 2022). "AP3S1 expression was positively correlated with most immunosuppressive genes in pan-cancer, such as CD274 (PD-L1), PDCD1 (PD-1), CTLA4, LAG3 and TIGIT." (PMID 35874816, 2022). "The expression of immune checkpoint (ICP) genes, such as PDCD1 (PD1), CD274 (PDL1), CTLA4, LAG3, and HAVCR2 (TIM3) has been utilized in predicting the response of patients to immune checkpoints therapy in a variety of cancers including PAAD." (PMID 35601487, 2022). "In this review, we will describe the function of LAG-3 and summarize the latest LAG-3 inhibitors in the clinic for cancer therapy." (PMID 35958563, 2022).
cancer (continued). "PDCD1, CD274, CTLA4, LAG3, C10orf54, and BTLA expression had positive correlations in most cancer types, and in approximately half of the cancer types, GBP1 expression is positively correlated with CD276 expression." (PMID 35222540, 2022). "LAG3 is a critical checkpoint inhibitor in the TME, described in various cancer forms, including cHL, with ongoing clinical trials (ClinicalTrials.gov identifier: NCT02061761)." (PMID 35008176, 2021). "The four important immune checkpoints (LAG3, TIM3, CTLA-4, and PD-1/PD-L1) were widely used in cancer immunotherapy." (PMID 33643388, 2021). "Recent studies focusing on immune checkpoints, such as CTLA-4, LAG-3, PD-1, TIGHT, and TIM-3, have uncovered that these can significantly regulate the cancer immune function of TICs, leading to the inhibition of immune surveillance." (PMID 34721523, 2021). "We found that FTL levels were positively related to PD-1 in 14/32 cancers (43.8%), PD-L1 in 10/32 (31.3%), CTLA4 in 13/32 (40.6%), TIM-3 in 26/32 (81.3%), LAG3 in 13/32 (40.6%), and LAIR1 in 26/32 (81.3%)." (PMID 33864445, 2021). "Lymphocyte-activation gene 3 (Lag3, also known as CD223) is an immune checkpoint inhibitory receptor, which is a cancer immunotherapy target." (PMID 33776654, 2021). "TIGIT expression mediated infiltrated immune cells and positively correlated with the expression of LAG3, CTLA4, PDCD1 (PD-1), CD274 (PD-L1), PDCD1LG2 (PD-L2) in most of the cancer types." (PMID 34795387, 2021). "FTH1 levels were positively related to PD-1 in 4/32 (12.5%) cancers, PD-L1 in 9/32 (28.1%), CTLA4 in 7/32 (21.9%), TIM-3 in 20/32 (62.5%), LAG3 in 2/32 (6.3%), and LAIR1 in 19/32 (59.4%)." (PMID 33864445, 2021). "The expression of immune checkpoint genes [e.g., PDCD1 (PD1), CD274 (PDL1), CTLA4, LAG3, and HAVCR2 (TIM3)] has been utilized in predicting the response of patients to ICB therapy in a variety of cancers including CC." (PMID 34733790, 2021). "As TIM3 and LAG3 are both potential targets for cancer immunotherapy, the clinical trial about coinhibition of TIM3 and LAG3 for cancer treatment is currently investigated." (PMID 33490273, 2021). "T cells in the TME of advanced cancer showed increased expression of PD1, CTLA4, CD39, PD-L2, LAG3, TIGIT, Tim3 and decreased expression of CD73." (PMID 34135436, 2021). "Along with CTLA-4, the transmembrane type I molecule lymphocyte-activation gene 3 (LAG-3; also known as CD223) was found to contribute to immune escape in cancer." (PMID 34681881, 2021). "The results revealed that CD161 was positively correlated with marker genes of exhausted T cells, immune activating genes, and immunosuppressive genes in pan-cancer, such as TIGIT, PDCD1, LAG3, CTLA4, STING1, CD96, and IDO1." (PMID 34305920, 2021). "Lymphocyte activation gene‐3 (LAG3), also known as CD223, is a potential cancer immunotherapeutic target because of its negative regulatory role on T cells." (PMID 34305910, 2021). "In our analysis, immune inhibitory checkpoint genes, LAG3, SIGLEC7, PD-1, PD-L2, TIM3, and others, showed significantly higher expression in EMT-high samples of several cancer types." (PMID 35096592, 2021). "Lymphocyte Activation Gene-3 (LAG3, CD223) served as another potential cancer immunotherapeutic target." (PMID 33648519, 2021). "Checkpoint interactions, such as PD-1:PD-L1, CTLA4:B7-1/2, T-cell immunoglobulin and mucin domain-3 (TIM-3):Galectin-9, and lymphocyte activation gene-3 (LAG-3):MHC class II, play an important role in immune evasion of cancers." (PMID 34208157, 2021). "In cancer patients, TIGIT expression is often correlated with the increased expression of inhibitory receptors (PD-1, LAG-3 and TIM-3) on CD8+ TILs." (PMID 34575943, 2021). "Both clusters also exhibited a cancer-specific exhaustive signature characterized by higher expression of checkpoint molecules (CTLA-4, LAG3, TIGIT)." (PMID 34921160, 2021).